LILRA1 (leukocyte immunoglobulin like receptor A1)
Description:
May act as receptor for class I MHC antigens.
Synonyms: LIR-6; CD85i; LIR6
Tractability: Antibody: its Gene Ontology location is reachable by antibodies, with high confidence; UniProt predicts a signal peptide or a membrane-spanning region.
Gene: Protein-coding gene on chromosome 19 (54,593,582 to 54,602,381, forward strand). Ensembl gene ENSG00000104974.
Subcellular location: Membrane
Pathways (Reactome):
Immune System: Immunoregulatory interactions between a Lymphoid and a non-Lymphoid cell
Gene Ontology:
Molecular function: protein binding; antigen binding; inhibitory MHC class I receptor activity; transmembrane signaling receptor activity
Biological process: cell surface receptor signaling pathway; defense response; immune response-inhibiting cell surface receptor signaling pathway; interleukin-10-mediated signaling pathway
Cellular component: plasma membrane; membrane
Genetic constraint (gnomAD): Loss-of-function variants: 52 observed, 51.15 expected, observed/expected ratio (o/e) 1.02, 90% interval 0.81 to 1.28. The synonymous counts are far from expectation, so gnomAD's model fits this gene poorly and the ratio says little. Missense variants: 660 observed, 582.02 expected, observed/expected ratio (o/e) 1.13, 90% interval 1.06 to 1.21. Synonymous variants: 305 observed, 232.56 expected, observed/expected ratio (o/e) 1.31, 90% interval 1.19 to 1.44.
Homologues: Orthologues: mouse Pira12 (49% identical), mouse Pira13 (48% identical), mouse Pira2 (48% identical), mouse Pira1 (48% identical), mouse Pirb (48% identical), rat Pirb (48% identical), mouse Lilra6 (47% identical), rat LOC134485274 (47% identical), rat Lilrb3 (42% identical), rat Lilrb2 (30% identical), mouse Lilra5 (27% identical), rat Lilrc2 (26% identical), and 1 more. Paralogues in human: LILRA2 (80% identical), LILRB1 (77% identical), LILRB2 (77% identical), LILRA6 (64% identical), LILRB3 (63% identical), LILRA4 (62% identical), LILRB5 (58% identical), LILRA5 (32% identical), LILRB4 (31% identical), KIR3DL2 (27% identical), KIR3DL1 (27% identical), KIR3DL3 (26% identical), and 13 more.
Diseases named in the same sentence as LILRA1 in open-access papers:
LILRA1 is named in the same sentence as 8 diseases in open-access papers, as found by Europe PMC text mining. Sharing a sentence is not in itself a finding about the gene and the disease. The quoted sentences say what the papers report.
asthma (1 paper, 2023). "CXCL10 was upregulated in asthma and LCP1, CCR1, PRKCB, IRAK2, LILRA1, and ZEB1 were significantly upregulated in COPD patients." (PMID 36829591, 2023).
clear cell renal cell carcinoma (1 paper, 2025). "LILRA1, LILRA2, LILRA5, LILRB1, LILRB2, and LILRB3 are differentially expressed across several cancer types, including lung squamous cell carcinoma, lung adenocarcinoma, papillary renal cell carcinoma, and clear cell renal cell carcinoma, suggesting a potential pan-cancer role for LILR family genes." (PMID 40843931, 2025).
cancer (3 papers, 2023 to 2025). A tumor composed of atypical neoplastic, often pleomorphic cells that invade other tissues. "Conversely, higher expression of these markers was associated with better survival rates in the SKCM cohort Consequently, although HLA-A/B/C and LILRA1/LILRA3/LILRB2 were commonly observed in non-responder TIMs, their association with post- ICB patient survival appears to be cancer-specific." (PMID 39034339, 2024).
infection (1 paper, 2016). The state of being infected such as from the introduction of a foreign agent such as serum, vaccine, antigenic substance or organism. "Our results demonstrated signalling from LILRA1 and LILRB5, indicating again a potential role for LILBR5 during infection." (PMID 26908331, 2016).
LILRA1 also shares sentences with these, for which no sentence is quoted: lung adenocarcinoma (1 paper); lung squamous cell carcinoma (1); papillary renal cell carcinoma (1); tumor (1).